FUNDC1 (FUN14 domain containing 1)
Diseases named in the same sentence as FUNDC1 in open-access papers (continued):
Sharing a sentence is not in itself a finding about the gene and the disease.
breast carcinoma (11 papers, 2019 to 2024). "Likewise, our previous study reported that high expression of FUNDC1 in breast cancer tissues is associated with poor outcomes and positively correlates with tumor size, stage and metastasis." (PMID 39668821, 2024). "Notably, FUNDC1 expression is positively associated with worse disease progression in breast cancer." (PMID 33634130, 2021). "Our previous research showed a correlation between high FUNDC1 expression and unfavorable prognosis in breast cancer." (PMID 39668821, 2024). "Micro-137 is a protective factor for breast cancer because it can target FUNDC1 to inhibit the occurrence of mitophagy." (PMID 35959490, 2022). "Several studies have reported high expression of FUNDC1 in malignant tumors such as breast cancer and cervical cancer." (PMID 34699308, 2022). "Here, we found that FUNDC1 upregulated in breast cancer cell lines and that knockdown of FUNDC1 suppressed breast cancer cell proliferation." (PMID 34272359, 2021). "Our study showed that miR-101 inhibited TNBC progression by mediating FUNDC1, which confirmed the suppressive role of miR-101 in breast cancer." (PMID 34272359, 2021). "Although a previous study proved that FUNDC1 regulates mitochondrial dynamics and mitophagy in mammalian cells, the expression status and role of FUNDC1 in breast cancer are unclear." (PMID 34272359, 2021). "Another study demonstrated that miR-137 could inhibit mitophagy by targeting FUNDC1 in breast cancer stem‐like cells." (PMID 39668821, 2024). "Moreover, a stimulative effect of FUNDC1 on cell proliferation was shown, which highlights its potential as a novel therapeutic target in breast cancer therapy." (PMID 39668821, 2024). "FUNDC1 promotes breast cancer progression via the calcium–NFATC1–BMI1 axis." (PMID 36831455, 2023). "Interestingly, a recent study has reported that FUNDC1 enhances breast cancer proliferation and migration via Ca2+ influx-mediated NFATC1 activation and translocation into the nucleus to activate BMI1 transcription." (PMID 33634130, 2021). "We further confirmed that the expression levels of FUNDC1 upregulated in breast cancer cell lines." (PMID 34272359, 2021). "Moreover, to the best of our knowledge, the relationship between FUNDC1 expression and tumor cell proliferation has been proved in cervical and breast cancers." (PMID 31998650, 2019). "Meanwhile, a lower expression of FUNDC1 was only found in one breast cancer dataset." (PMID 31998650, 2019). "Similarly, another study revealed that the expression level of FUNDC1 in breast cancer tissues was significantly greater than that in normal breast tissues, and higher expression of FUNDC1 was related to worse disease progression in breast cancer patients." (PMID 39472438, 2024). "Moreover, overexpression of FUN14 domain-containing 1 (FUNDC1), a MAM protein, could be a diagnostic and prognostic marker for breast cancer, as it triggers cell proliferation, migration, and invasion." (PMID 38172597, 2024). "However, in breast cancer, FUNDC1 likely functions as a tumor promoter through different mechanisms, in which depletion of FUNDC1 blocks TNBC cell proliferation by deregulating Ca2+ release from the ER and through NFATC1 activation, which are reversed by overexpression of BMI1." (PMID 36831455, 2023). "FUNDC1 knockdown by siRNA alters NFATC1 activity and inhibits the proliferation and metastasis of breast cancer cells." (PMID 38172597, 2024). "Furthermore, FUNDC1-involved MAMs can promote calcium transport to cytoplasm, making nuclear factor of activated T cells 1 (NFATC1) dephosphorylated, and then Bmi1 polycomb ring finger oncogene (BMI1) is upregulated, thus promoting the progression of breast cancer." (PMID 35959490, 2022).
cervical cancer (11 papers, 2017 to 2024). A primary or metastatic malignant neoplasm involving the cervix. "The overexpression of FUNDC1 is associated with tumor progression and poor patient prognosis, indicating a tumor-promoting role of FUNDC1 in cervical cancer." (PMID 35201480, 2021). "Notably, depletion of FUNDC1 in patients with cervical cancer, where high levels of FUNDC1 are associated with a poor prognostic outcome, significantly enhances cell sensitivity to cisplatin and ionizing radiation." (PMID 33946271, 2021). "In the cancer cells of early‐stage cervical cancer patients, FUNDC1 had higher expression levels than the normal cells, and high FUNDC1 expression was negatively correlated with the patient prognosis." (PMID 36200262, 2022). "FUNDC1 overexpression stimulates the development of cervical cancer cells, while inhibition of its expression improves susceptibility to cisplatin and ionizing radiation." (PMID 35326612, 2022). "In cervical cancer, the expression of FUNDC1 is significantly upregulated in tumors as compared to normal tissues." (PMID 35201480, 2021). "This high FUNDC1 expression is negatively correlated with tumor progression and patient prognosis, indicating a potential role of FUNDC1 in the suppression of tumor growth of cervical cancer." (PMID 33262988, 2020). "In early-stage cervical cancer patients, it was found that FUNDC1 has a higher expression level than adjacent normal cells." (PMID 32587855, 2020). "In this study, for the first time, we examined the FUNDC1 expression profile in tumor tissues of patients with cervical cancer, and found that high FUNDC1 expression can be used as an independent predictor for poor prognoses of patients." (PMID 28719148, 2017). "In this study, immunohistochemistry was used to detect FUNDC1 protein expression in paraffin‐embedded specimens of postoperative tumor tissues from 82 cervical cancer patients and in 35 samples of normal adjacent cervical tissue as the control." (PMID 28719148, 2017). "Our results suggested that inhibition of FUNDC1 promoted the death of cervical cancer cells under the effects of cisplatin and ionizing radiation." (PMID 28719148, 2017). "Immunohistochemistry and Western blotting were applied to detect the expression of FUNDC1, and small‐hairpin RNA was applied to inhibit the expression of endogenous FUNDC1 in cervical cancer cells." (PMID 28719148, 2017). "Our results also suggest that inhibition of FUNDC1 in cervical cancer cells promotes DNA damage and apoptosis pathway activation induced by cisplatin and ionizing radiation." (PMID 28719148, 2017). "Our data suggest that depletion of FUNDC1 inhibits the proliferation of Hela and Caski cervical cancer cells and promotes apoptosis." (PMID 28719148, 2017). "To explore the roles of FUNDC1 in the radiotherapy response of cervical cancer cells, we infected HeLa and Caski cells with lentivirus carrying FUNDC1 short‐hairpin RNA (shRNA#1 and shRNA#2) and the corresponding control Scramble shRNA (Control groups)." (PMID 28719148, 2017). "We also investigated the possible biological mechanisms of FUNDC1 in the sensitivity of cervical cancer cells to chemoradiotherapy." (PMID 28719148, 2017). "Through detecting FUNDC1 expression in the postoperative tumor tissue for 82 patients with early‐stage cervical cancer, we found significantly higher expression of FUNDC1 compared with that in normal cervical tissues." (PMID 28719148, 2017). "Moreover, depletion of FUNDC1 in cervical cancer cells inhibited cell viability and enhanced sensitivity to cisplatin and ionizing radiation." (PMID 39668821, 2024). "Moreover, blocking FUNDC1 has been noted to increase the responsiveness of cervical cancer cells to both cisplatin and radiation therapy." (PMID 38913914, 2024). "Similarly, inhibition of FUNDC1 also improved the sensitivity of cervical cancer cells to cisplatin." (PMID 36200262, 2022).
cervical cancer (continued). "Furthermore, FUNDC1 overexpression predicts a poor prognosis and is a possible target for improving chemoradiotherapy effects in cervical cancer patients." (PMID 35326612, 2022). "Moreover, overexpression of FUNDC1 promotes growth of cervical cancer cells, and inhibition of expression enhances the sensitivity to cisplatin treatment and ionizing radiation." (PMID 32587855, 2020). "In cervical cancer, the expression of FUNDC1 was higher in tumors than in adjacent normal tissues." (PMID 33262988, 2020). "Thus, the rate of high FUNDC1 protein expression in cervical cancer tissues was significantly higher than that in normal cervical tissues (**P < 0.01)." (PMID 28719148, 2017). "Therefore, this study aimed to explore the relationship between the expression of FUNDC1 and the prognosis of patients with cervical cancer." (PMID 28719148, 2017). "Our data suggested that FUNDC1 can be used as a prognostic biomarker in patients with cervical cancer, and may be a new therapeutic target to improve the antitumor effects of chemoradiotherapy." (PMID 28719148, 2017). "Furthermore, we used Real‐time PCR to measure the mRNA level of FUNDC1 in 12 paired cervical cancer (CC) and adjacent normal cervical tissues (ANTs)." (PMID 28719148, 2017). "The aim of this study was to explore the expression and roles of FUNDC1 in cervical cancer." (PMID 28719148, 2017). "In addition, our results suggest that FUNDC1 promotes the proliferation of cervical cancer cells and inhibits apoptosis." (PMID 28719148, 2017). "High expression of FUNDC1 and the prognosis of patients with cervical cancer were correlated negatively, which could be used as an independent prognostic factor for overall survival and disease‐free survival." (PMID 28719148, 2017). "Furthermore, FUNDC1 protein expression could be used as an independent prognostic factor for patients with early‐stage cervical cancer, and it was negatively correlated with their OS and DFS." (PMID 28719148, 2017). "Therefore, FUNDC1 may become a new therapeutic target for cervical cancer and other tumors, and improve the prognosis of cancer patients." (PMID 28719148, 2017). "Depletion of FUN14 domain-containing protein 1 (FUNDC1) significantly enhances cell sensitivity to cisplatin and ionizing radiation in cervical cancer." (PMID 36289190, 2022). "We conducted statistical analysis of the differences in FUNDC1 protein expression in overall survival (OS) and disease‐free survival (DFS) of the 82 cervical cancer patients." (PMID 28719148, 2017). "Compared with corresponding adjacent noncancerous cervical tissues, the expression of FUNDC1 in cervical cancer cells was significantly increased." (PMID 28719148, 2017).
diabetes (11 papers, 2020 to 2025). "Specific knockout of FUNDC1 by cardiomyocytes can eliminate the formation of MAMs induced by diabetes, prevent mitochondrial fragmentation and mitochondrial calcium overload, suggesting that inhibition of FUNDC1 is a potential target of DCM." (PMID 41366202, 2025). "Diabetes increases FUNDC1 expression and aberrant MAM formation in cardiomyocytes, resulting in an increase in mitochondrial Ca2+ levels, mitochondrial dysfunction, and cardiac dysfunction." (PMID 35450404, 2022). "Diabetes was shown to suppress AMP-activated protein kinase that initiated FUNDC1-mediated MAM formation, resulting in mitochondrial dysfunction and cardiomyopathy." (PMID 35011599, 2021). "Wu's study showed that FUNDC1 is important in mediating MAMs formation in diabetes, with high glucose increasing FUNDC1 levels, IP3R2 levels, and MAMs formation, resulting in increased Ca2+ levels, mitochondrial dysfunction, and deterioration of cardiac function." (PMID 35450404, 2022). "This notion received support from a very recent study in which diabetes-induced chronic enrichment of MAMs in podocytes and disruption of MAMs formation by knockdown of FUNDC1 expression, a key tether for MAMs, antagonized mitochondrial dysfunction and the progression of renal damage in db/db mice." (PMID 32952849, 2020). "It was concluded in the study that diabetes facilitates Fundc1-mediated MERC formation, and inhibition of Fundc1 could be a potential therapy for diabetic CM." (PMID 33425917, 2020). "Diabetes may induce the formation of MAMs by downregulating AMPK, and activation of AMPK may play a part in ameliorating diabetic cardiomyopathy by downregulating FUNDC1 and FUNDC1-associated MAMs." (PMID 38828457, 2024). "In cardiomyocytes from a mouse model of diabetes, FUNDC1 was highly expressed and might promote MAM formation by interacting with IP3R2, thereby increasing Ca2+ and FIS1 expression in mitochondria, ultimately leading to mitochondrial dysfunction and impaired myocardial structure and function." (PMID 39506876, 2024). "Consequently, the inhibition of FUNDC1 in cardiomyocytes affected by diabetes may lead to the restoration of mitochondrial function and the preservation of cardiac function." (PMID 37298100, 2023).
ischemia (11 papers, 2018 to 2025). A hypoperfusion of the BLOOD through an organ or tissue caused by a PATHOLOGIC CONSTRICTION or obstruction of its BLOOD VESSELS, or an absence of BLOOD CIRCULATION. "Some work suggested that FUNDC1 can maintain mitochondrial function by inducing the mitophagy of cardiomyocytes, thereby protecting myocardial damage caused by ischemia and reperfusion." (PMID 34115550, 2021). "However, inhibiting of FUNDC1-mediated mitophagy will aggravate the heart damage caused by ischemia-reperfusion injury." (PMID 34115550, 2021). "It was shown that knockdown of BNIP3L/Nix in differentiating cardiac progenitor cells increased FUNDC1 transcripts, and vice versa, in an adult mouse model of ischemia." (PMID 41369393, 2025). "Ischemic or hypoxic stimulus alleviates FUNDC1 phosphorylation at Tyr18, leading to induction of mitophagy in ischemia." (PMID 29540794, 2018). "OPA1-induced mitophagy and FUNDC1-dependent mitophagy could offer cardioprotection against ischemia, while the knockout of Parkin causes extensive cardiac injury due to mitochondrial dysfunction and mitophagy inhibition." (PMID 35096821, 2021). "In myocardial ischemia/reperfusion, studies have found that hypoxic preconditioning could induce FUNDC1-dependent mitophagy to resist ischemia/reperfusion injury." (PMID 33424757, 2020).
cardiomyopathy (8 papers, 2021 to 2025). A disease of the heart muscle or myocardium proper. "In particular, Males Only DMRs selected by machine learning feature selection were able to distinguish CHD from non-CHD samples and frequently mapped to genes associated with CHDs or cardiomyopathies, including FUNDC1, ETV5, SYT9, CAMTA1, GRIA4, and IGF1R." (PMID 37803336, 2023). "Cardiac-specific deletion of FUNDC1 improves mitochondrial function and attenuates cardiomyopathy in diabetic mice, confirming the causative role of FUNDC1 in this disorder." (PMID 35450404, 2022). "FUN14 domain containing 1 (FUNDC1) is a mitochondrial membrane protein participating in the regulation of mitochondrial integrity in multiple diseases although its role in DOX cardiomyopathy remains elusive." (PMID 36470869, 2022). "In summary, their works demonstrated that coordination of FUNDC1-mediated mitophagy and mtUPR plays a key role in protection against LPS-induced cardiomyopathy and shed light on a new avenue toward the understanding and treatment of SICM." (PMID 34975548, 2021). "In a model of doxorubicin‐induced cardiomyopathy and fibrosis, activating the AMPK/ULK1/FUNDC1 pathway reduces ROS levels, improves mitochondrial membrane potential, and increases mitophagy, thereby ameliorating cardiomyopathy." (PMID 40535916, 2025).
Hyperglycemia (8 papers, 2021 to 2026). An increased concentration of glucose in the blood. "The AMPK phosphorylation at Thr172 significantly decreased in hyperglycemia-related hearts and concomitantly associated with an increase of FUNDC1, which induces aberrant MAM formation reversibly." (PMID 39464632, 2024). "On top of that, in STZ-induced cardiac remodeling, the increase of FUNDC1 mediated by hyperglycemia interacts with IP3R2 and inhibits IP3R2 ubiquitination and proteasomal degradation." (PMID 39464632, 2024). "Similarly, while Pgam5 deletion maintained the transcription of Parkin, Fundc1, and Bnip3, this effect was abrogated by Phb2 siRNA in hyperglycemia-treated cardiomyocytes." (PMID 38818468, 2024). "In this cycle, hyperglycemia impairs both the PINK1/Parkin-mediated mitophagy pathway and ubiquitin-independent pathways like FUNDC1 under hypoxic conditions, leading to the accumulation of damaged mitochondria." (PMID 41793088, 2026). "Extracellular hyperglycemia and metabolic dysregulation create an energy stress in DCM, which reduce the interaction of OPA1 and FUNDC1, increasing mitochondrial fragmentation." (PMID 35450404, 2022). "We speculate that extracellular hyperglycemia and metabolic dysregulation in DCM might reduce the interaction of OPA1 and FUNDC1, thereby increasing mitochondrial fragmentation." (PMID 35450404, 2022).
Insulin resistance (8 papers, 2019 to 2024). Increased resistance towards insulin, that is, diminished effectiveness of insulin in reducing blood glucose levels. "Recent study has shown that BNIP3-, NIX-, and FUNDC1-mediated mitophagy plays a critical role in the treatment of lipid metabolism, hepatocellular carcinoma, hepatic insulin resistance, alcoholic liver disease, hepatic steatosis, and liver injury." (PMID 31649547, 2019). "Interestingly, the mitophagy receptor FUNDC1 dysfunction significantly affects adipose inflammatory metabolism and insulin resistance, compromising adipocyte production and exacerbating diet-induced obesity." (PMID 38982993, 2024). "However, evidence from other studies showed that ablation of autophagy-related gene 7 (Atg7) or FUN14 domain-containing 1 (Fundc1) alleviated insulin resistance." (PMID 33339212, 2020). "Mechanistically, the hyperactivation of the MAPK/JNK pathway precipitates insulin resistance, a condition ameliorable through the abrogation of MAPK8/JNK1 in the FUNDC1 knockout model." (PMID 38982993, 2024).
myocardial infarction (8 papers, 2019 to 2025). Gross necrosis of the myocardium, as a result of interruption of the blood supply to the area, as in coronary thrombosis. "Previous studies have implicated the AMPK pathway in the regulation of FUNDC1-mediated mitophagy in post-myocardial infarction models." (PMID 41292702, 2025). "In cardiac-specific FUNDC1 KO mice, cardiac function is reduced and infarcted areas are larger following myocardial infarction." (PMID 36632466, 2023). "Ablation of MST1 gene preserves FUNDC1 levels and mitophagy, thus reducing myocardial infarction size and preserving cardiac function." (PMID 35645834, 2022). "CK2α induces FUNDC1 inactivation through a post-transcriptional modification at Ser13, thereby inhibiting mitophagy, disrupting mitochondrial homeostasis, promoting cardiomyocyte death and expansion of myocardial infarction area, and cardiac insufficiency." (PMID 36632466, 2023). "Mst1 knockout mice could reverse FUNDC1 expression and markedly reduced the myocardial infarction (MI) size." (PMID 31781358, 2019). "We focused on cardiac mitophagy during and following myocardial infarction by highlighting the role and the regulation of PI NK1/parkin-; FUNDC1-; BNIP3- and BNIP3L/NIX-induced mitophagy during ischemia and reperfusion." (PMID 35053316, 2022). "In related studies, Beclin1+/− and FUN14 domain-containing 1 (FUNDC1) knockout and transgenic mouse models, in conjunction with starvation and myocardial infarction models, suggest that mitophagy, rather than general autophagy, plays a cardioprotective role by regulating mitochondrial function." (PMID 37304955, 2023).